PTX3 (pentraxin 3)
Diseases named in the same sentence as PTX3 in open-access papers (continued):
Sharing a sentence is not in itself a finding about the gene and the disease.
prostate carcinoma (continued). "Odds ratios (ORs) and 95% confidence intervals (CIs) of the clinical status and PTX3 rs2120243 and rs3816527 genotypic frequencies in 705 patients with prostate cancer." (PMID 39187920, 2024). "In preclinical models, Ptx3 deficiency was associated to higher susceptibility to chemical carcinogenesis, while in human prostate cancer PTX3 expression is progressively reduced in high-grade prostatic intraepithelial neoplasia and invasive tumor areas." (PMID 37025408, 2023). "In fact, serum PTX-3 curve proved better performance in identifying prostate cancer patients than the serum PSA curve." (PMID 36499628, 2022). "Falagario and colleagues proved the out performance of PTX-3 accuracy in detecting prostate cancer in comparison with PSA." (PMID 36499628, 2022). "Accordingly, we also demonstrated the role of PTX3 in prostate cancer development, highlighting the link between inflammation, complement activation, and neoplasia progression." (PMID 34572075, 2021). "Considering the limited data on the role of Complement activation in the development of prostate cancer, the aims of present study were to elucidate the potential relationship between PTX3 and Complement cascade activation in this contest." (PMID 33110136, 2020). "In prostate cancer patients, circulating levels of PTX3 were higher compared to patients with prostatic inflammation, while serum levels of prostate-specific antigen (PSA) and CRP were not different between the two groups." (PMID 31019517, 2019). "Expression levels of PTX3 in prostatic tissue and its serum levels predict the progression of prostate inflammation to prostate cancer." (PMID 31744201, 2019). "In tissue samples from prostate cancer patients, PTX3 is expressed at higher levels compared to patients with prostatic inflammation." (PMID 31019517, 2019). "Previous observations had shown that FGF8b and FGF2 play a key role in prostate cancer and that PTX3 overexpression inhibits the FGF8b/FGF2-driven growth of TRAMP-C2 tumors, an androgen-responsive murine model of prostate carcinoma." (PMID 25912421, 2015). "A previous study reported that PTX3 expression is silenced in prostate cancer cells at a relatively early stage during tumor progression." (PMID 24457902, 2014). "Similarly, compared to patients with prostatic inflammation or BPH, prostate cancer patients exhibited elevated peripheral PTX3 levels, which increased over time, suggesting a tumor-promoting role of PTX3 during prostatic inflammation or BPH." (PMID 41479916, 2025). "PTX3 may act as an antitumor agent in prostate cancer by targeting FGF2 and FGF8b to exert antiangiogenic and antineoplastic effects, as previously discussed." (PMID 41479916, 2025). "Even more, PTX-3 could be used as a target for the prevention of prostate cancer due to its predictive value (87.1% positive predictive value and 97.2% negative predictive value)." (PMID 36499628, 2022). "Besides the role of PTX3 as a biomarker, recent studies have demonstrated that PTX3 increased expression in prostate cancer biopsies colocalized with C1q deposits and correlated with augmented C3aR and C5aR receptors." (PMID 34572075, 2021). "In conclusion, in prostate cancers, elevated PTX3 levels could reflect the attempt of a reparative process aimed to counteract systemic inflammation or genetic instability that drives carcinogenesis." (PMID 34572075, 2021). "There might be two potential limits in the development of PTX3 as a prostate cancer specific biomarker: its potential expression in other neoplasia and its association with an inflammatory status." (PMID 33110136, 2020). "Interestingly, we found a correlation between PTX3 and C1q deposits in patients of group A who developed prostate cancer." (PMID 33110136, 2020). "Our data support the hypothesis that in prostate cancer PTX3 may play a role in the priming of the Complement enzymatic cascade." (PMID 33110136, 2020).
prostate carcinoma (continued). "Also, linear regression analysis showed a significant correlation between 18F–choline uptake and the number of vimentin, RANKL, VDR, or PTX3 positive prostate cancer cells." (PMID 31614564, 2019). "Since PTX3 acts as a natural antagonist for FGFs, the changes in PTX3 level may determine the angiogenic and tumorigenic potential of osteoblastic prostate cancer cells, presumably by inhibiting bone-forming activity exerted by FGFs." (PMID 24457902, 2014). "Additionally, an inverse correlation was observed between the number of PD-L1-positive cells and PTX3 expression in prostate cancer cells, indicating the need for further research to understand the interplay between PTX3 and PD-L1 in developing effective prostate cancer management strategies." (PMID 41479916, 2025). "Many studies have identified PTX3 promoting increased cancer cells proliferation and migration, as well as decreased cancer cell apoptosis across different types of cancers, such as esophageal squamous cell carcinoma, lymphomas, leukemias, glioblastomas, and renal and prostate cancers." (PMID 37408184, 2023). "However, PTX3 also has the inhibitory effect on angiogenesis and is able to moderate malignant progression in bladder cancer, multiple myeloma, fibrosarcoma, and prostate cancer." (PMID 35982954, 2022). "In line with its antitumoral activity, PTX3 immune reactivity that is normally abundant in the prostate gland has been shown to disappear in tumor biopsies taken from high-grade intraepithelial neoplasias and prostatic adenocarcinomasin experimental models of prostate cancer." (PMID 34048179, 2021). "In this context, the close relationship between the Complement system and PTX3 may represent an interesting pathogenic mechanism, although experimental data on the activation of the Complement cascade in prostate cancer are lacking." (PMID 33110136, 2020). "Similar results were obtained in another study that compared 40 biopsies of prostate cancer patients with 40 biopsies of benign prostatic hyperplasia and assessed a sharp increase in CD59 expression and colocalization with PTX3." (PMID 34572075, 2021). "Also, it is important to emphasize that BM− group showed the same number of PTX-3-positive cells of BL, suggesting that the presence of PTX-3-positive cells could represent a reliable predictive element for the development of bone metastasis from prostate cancer." (PMID 30627063, 2018). "Here, in agreement with previous findings, we show that PTX3 overexpression or treatment with the PTX3-derived small molecule FGF trap NSC12 result in a significant inhibition of the growth of TRAMP-C2 tumor grafts, a murine model of prostate cancer." (PMID 29137286, 2017). "Accordingly, the FGF antagonist long pentraxin-3 (PTX3) and the PTX3-derived small molecule FGF-trap NSC12 have been shown to inhibit the growth and vascularization of different FGF-dependent tumor types, including prostate cancer." (PMID 29137286, 2017). "The C1q/PTX3 deposits without resulting in C5b-9 activation are extensively present in BPH patients who later develop into prostate cancer." (PMID 41479916, 2025). "A strong PTX3 expression is observed in tumor samples of prostate cancer patients with bone metastases, compared to those without bone metastases or without cancer." (PMID 41479916, 2025). "A single-center cohort study revealed PTX3 and C1q deposits in prostate cancer samples, which were absent in benign prostatic hyperplasia (BPH)." (PMID 41479916, 2025). "Therefore, PTX-3 appears asa promising screening candidate as PSA, which is the only biomarker used until now in prostate cancer screening and is characterized by a high false positive rate and low accuracy." (PMID 36499628, 2022). "Overproduction of PTX3 in these animals was found to powerfully inhibit tumoral growth, neovascularization, and metastatic activity of heterotropic, orthotropic, and autocrine models of FGF-dependent lung and prostate cancers." (PMID 34048179, 2021).
prostate carcinoma (continued). "Surprisingly, in prostate cancer cell lines, non-bone metastatic DU-145 cells expressed much higher levels of PTX3 expression compared to bone metastatic PC-3 cells, although PTX3 expression was not responsive to TNFα treatment." (PMID 24457902, 2014). "Conversely, PTX3 overexpression in transgenic mice or treatment with the FGF inhibitor NSC12 result in a significant inhibition of the growth and vascularization of TRAMP-C2 tumor grafts, a murine model of prostate cancer, that were paralleled by a decrease of mast cell infiltrate into the lesion." (PMID 29137286, 2017).
chronic kidney disease (29 papers, 2012 to 2025). Impairment of the renal function secondary to chronic kidney damage persisting for three or more months. "Patients on hemodialysis who had end-stage renal disease had significantly higher PTX3 levels, which was linked to a lower five-year survival rate." (PMID 40470435, 2025). "Previous studies have demonstrated that patients with PAD and CAD have elevated levels of PTX3, and PTX3 can predict both all-cause mortality and cardiovascular mortality in patients with chronic kidney disease." (PMID 40278353, 2025). "Our aim was to study how specific polymorphisms of IL6 and PTX3 encoding genes affect the inflammatory response and outcome of end-stage renal disease (ESRD) patients on dialysis." (PMID 34285273, 2021). "Recently, several clinical investigations have demonstrated that elevated plasma PTX3 levels are associated with cardiovascular and chronic kidney diseases (CKD)." (PMID 24350299, 2013). "Recent reports have demonstrated that elevated plasma long pentraxin 3 (PTX3) levels are associated with cardiovascular and chronic kidney diseases." (PMID 24350299, 2013). "Smaller evaluations in patients with chronic kidney disease demonstrate an association between PTX3 levels and prevalent as well as future CVD." (PMID 22319633, 2012). "Elevated PTX3 levels have been linked to the severity of kidney damage, and its levels may help identify patients at risk of developing end-stage renal disease." (PMID 40299501, 2025). "However, although increased PTX3 plasma levels have been associated with aging-related diseases, including chronic kidney disease, the relationship between PTX3 and oxidative stress in aging remains to be elucidated." (PMID 32012711, 2020). "This is consistent with the potential occurrence of elevated PTX3 levels in blood due to intercurrent systemic infections or non-infectious reasons such as injuries, cardiac diseases, and chronic kidney disease." (PMID 35956001, 2022). "In chronic kidney disease, the increase in protein levels of PTX3 has been correlated with GFR declines and cardiovascular complications, however, little is still known of the role of PTX3 in early setting as I/R-induced acute kidney injury." (PMID 33875620, 2021). "Elevated levels of PTX-3 have been found in septic shock, chronic kidney disease, stroke, and a variety of cardiovascular diseases." (PMID 32670996, 2020). "Recently, several clinical investigations have demonstrated that higher plasma PTX3 levels are associated with cardiovascular diseases and with lower GFR and independently predict incidence of chronic kidney diseases." (PMID 28191789, 2017). "PTX3 is notably elevated in patients with terminal chronic kidney disease and the relationship between PTX3 and cardiovascular morbidity suggests a possible connection between PTX3 and arteriosclerosis and CVD in patients undergoing hemodialysis therapy." (PMID 26903710, 2016). "Elevated PTX3 levels were described in various infectious and inflammatory diseases, including chronic kidney disease." (PMID 25855355, 2015). "Same authors in another clinical study observed that plasma PTX3 levels are higher in both patients with chronic kidney disease and with chronic kidney disease + periodontal disease than healthy controls." (PMID 22966213, 2012). "Since PTX3 is more sensitive than hs-CRP in distinguishing stages of DN, it holds promise as a more reliable biomarker for assessing kidney function and predicting the risk of chronic kidney disease (CKD) in diabetic patients." (PMID 40299501, 2025). "Indeed, PTX3 has been indicated as a potential biomarker of vascular endothelial dysfunction in several diseases, including chronic kidney disease, preeclampsia and several vascular diseases." (PMID 33875620, 2021). "In addition, elevated levels of PTX3 were found in the plasma of patients with chronic kidney disease and diabetic nephropathy." (PMID 31780874, 2019).
chronic kidney disease (continued). "The relationship between PTX3 and various acute and chronic kidney diseases is a hot topic." (PMID 29725602, 2018). "In addition, patients with end-stage renal disease show inverse correlations of plasma PTX3 levels with BMI and waist circumference." (PMID 24705587, 2014). "The current study provided the first evidence that decreased plasma PTX3 levels are associated with T2DM and DN in Malay men and also suggested that PTX3 may have different effects in DN and chronic kidney diseases." (PMID 24350299, 2013). "There is evidence that PTX3 levels increase in various chronic inflammatory diseases such as atherosclerotic lesions, coronary artery disease, small vessel vasculitis, rheumatoid arthritis, and chronic kidney disease." (PMID 22966213, 2012). "PTX3 was also increased in chronic kidney disease (CKD) as a result of the inflammatory process starting at the early stages, which is also interrelated to psoriasis." (PMID 35888704, 2022). "PTX3 plasma levels also increase in patients with chronic kidney disease (CKD), and correlate with the severity of the disease." (PMID 31057548, 2019). "Elevated systemic pentraxin 3 (PTX3) levels appear to be a powerful marker of inflammatory status and a superior outcome predictor in patients with chronic kidney disease (CKD)." (PMID 23658833, 2013). "In patients with chronic kidney disease and those with ESRD receiving HD, increased, but not increasing, level of PTX3 is strongly predictive of poor clinical outcome and may be independent risk factors of mortality." (PMID 25587447, 2014).
Stroke (26 papers, 2014 to 2025). Sudden impairment of blood flow to a part of the brain due to occlusion or rupture of an artery to the brain. "High levels of PTX3 have been shown to be associated with worse outcomes in other organs including the brain following a stroke, and with low levels have reported to increase tumor development risk." (PMID 39404377, 2024). "Collectively, these findings demonstrate the potential and clinical relevance of PTX3 as a promising therapeutic target, providing sustained long-term post-stroke neurovascular repair and reducing the loss of neurons." (PMID 30315331, 2018). "Ptx3 encodes the acute-phase protein pentraxin-3, important in the classical complement pathway that has been shown to promote neurogenesis and angiogenesis in rodent models of stroke and to regulate the blood–brain barrier." (PMID 39796165, 2025). "Elevated PTX3 levels have been associated with worse stroke severity and poor functional outcomes." (PMID 40542581, 2025). "As a potential predictor of stroke prognosis, PTX3 could provide valuable insights for risk stratification and targeted therapeutic interventions." (PMID 40542581, 2025). "Collectively, our results suggest that PTX3 may be an effective post-stroke treatment option reducing neuronal loss and promoting long-term repair." (PMID 30315331, 2018). "Notably, analysis of 341 DE mRNA associated with stroke (259 upregulated, 82 downregulated) in the IR group revealed upregulation of genes like Ccl2, Cxcl1, C3, Serpine1, Adamts7, Csf3, Ptx3, MMP8, Lif, and Lcn2, and downregulation of Gdf10, Agtr2 and Shank3." (PMID 39170713, 2024). "Additionally, our PTX3 siRNA approach worked in the mouse model of white matter stroke, and importantly, mice that received PTX3 siRNA on day 0 showed exacerbated myelin damage/loss on day 3 after stroke compared to mice with control siRNA injection." (PMID 33314664, 2021). "Recent clinical studies suggest that pentraxin 3 (PTX3), which is known as an acute‐phase protein that is produced rapidly at local sites of inflammation, may be a new biomarker of disease risk for central nervous system disorders, including stroke." (PMID 33314664, 2021). "In fact, PTX3 surpasses SERPINA3 and hsCRP, in that order, as a long-term prognostic marker of the endpoint consisting of all-cause mortality or MI or stroke in men." (PMID 39897419, 2025). "Recent studies suggest PTX3 plays a critical role in cerebrovascular pathology, particularly in stroke." (PMID 40542581, 2025). "A compromised resolution of brain edema and glial scar formation was observed after ischemic brain injury in PTX3 deficient mice, and astrocyte-derived PTX3 maintained blood-brain barrier integrity after stroke." (PMID 35656007, 2022). "Accordingly, peripheral PTX3 levels are increased after experimental stroke in mice, and plasma PTX3 levels correlate with mortality after ischemic stroke in humans." (PMID 36012705, 2022). "Among others, it should be of great interest to study brain microvascular EC (BMVEC)-derived PTX3 and its role in the protective effect observed in neurons after seizures or strokes." (PMID 36362273, 2022). "Nevertheless, in keeping with the observation that the serum levels of PTX3 are increased after stroke and in Parkinson’s disease, the levels of PTX3 in the blood of P35 twitcher mice were significantly increased when compared to Galcwt animals." (PMID 36012705, 2022). "Serum PTX3 levels were significantly increased (p < .001) in stroke patients (3.14 ± 1.23 ng/ml) as compared with those in the control group (2.44 ± 0.74 ng/ml)." (PMID 33210471, 2021). "VEGF and MMP‐9 are detrimental to BBB integrity but beneficial for compensatory angiogenesis, whereas PTX3 is beneficial for BBB integrity during the acute phase of stroke but harmful for compensative angiogenic responses during the chronic phase." (PMID 33314664, 2021).